CES5A (carboxylesterase 5A)
Description:
Involved in the detoxification of xenobiotics and in the activation of ester and amide prodrugs.
Synonyms: Cauxin; CES7; FLJ31547; CES4C1; CES5; HEL126
Tractability: Small molecule: it belongs to a druggable protein family. Antibody: UniProt places it where antibodies can reach, with medium confidence; UniProt predicts a signal peptide or a membrane-spanning region; its Gene Ontology location is reachable by antibodies, with medium confidence.
Gene: Protein-coding gene on chromosome 16 (55,846,154 to 55,956,031, reverse strand). Ensembl gene ENSG00000159398.
Subcellular location: Secreted
Gene Ontology:
Molecular function: carboxylesterase activity
Cellular component: extracellular region
Genetic constraint (gnomAD): Loss-of-function variants: 55 observed, 54.65 expected, observed/expected ratio (o/e) 1.01, 90% interval 0.81 to 1.26. The upper end of that interval is the gene's LOEUF score, 1.26, which puts it in group 5 of 6, group 1 being the genes least tolerant of losing a copy. Missense variants: 659 observed, 645.09 expected, observed/expected ratio (o/e) 1.02, 90% interval 0.96 to 1.09. Synonymous variants: 258 observed, 257.66 expected, observed/expected ratio (o/e) 1, 90% interval 0.9 to 1.11.
Homologues: Orthologues: chimpanzee CES5A (98% identical), macaque CES5A (93% identical), rabbit CES5A (78% identical), pig CES5A (74% identical), mouse Ces5a (70% identical), rat Ces5a (69% identical), zebrafish ces2a (40% identical), zebrafish ces3 (39% identical), zebrafish nlgn2b (33% identical), zebrafish nlgn3b (31% identical), Drosophila melanogaster Gli (30% identical), Caenorhabditis elegans ace-4 (28% identical), and 48 more. Paralogues in human: CES2 (43% identical), CES3 (43% identical), CES1 (42% identical), CES4A (41% identical), NLGN2 (35% identical), NLGN1 (33% identical), NLGN4X (33% identical), NLGN4Y (33% identical), NLGN3 (32% identical), ACHE (31% identical), BCHE (31% identical), CEL (29% identical), and 1 more.
Diseases named in the same sentence as CES5A in open-access papers:
CES5A is named in the same sentence as 3 diseases in open-access papers, as found by Europe PMC text mining. Sharing a sentence is not in itself a finding about the gene and the disease. The quoted sentences say what the papers report.
Cognitive impairment (1 paper, 2023). Abnormal cognition is characterized by deficits in thinking, reasoning, or remembering. "As an expected role of carboxylesterase family genes, the CES5A protein can result in high levels of cholesterol and choline esterase, alterations of which impact cognitive impairment, especially on memory in aging rats." (PMID 36658485, 2023).
CES5A also shares sentences with these, for which no sentence is quoted: Infertility (1 paper); Obesity (1).